MR1 (major histocompatibility complex, class I-related)
Diseases named in the same sentence as MR1 in open-access papers (continued):
Sharing a sentence is not in itself a finding about the gene and the disease.
cancer (continued). "Since MR1 is a member of a family of non-classical MHC proteins, this TCR should enable recognition of cancer cells in a wide range of patients while minimizing off-target effects." (PMID 35720306, 2022). "A more recent study highlighted the role of MR1 protein in a non-MAIT T cell receptor’s recognition and killing of cancer cells in most human cancer types." (PMID 33919687, 2021). "The monomorphic major histocompatibility complex class I-related gene protein (MR1) can be used in targeting and destroying cancer cells, while being nonharmful for noncancerous cells." (PMID 32906638, 2020). "Again, this reactivity was not cancer-specific, with A4.TCR-T and C1.TCR-T producing IFN-γ and granzyme B in response to B cells and monocytes from MR1*04 heterozygous donors and not in response to MR1*01/02 donors." (PMID 39445059, 2024). "Along these lines, a genome-wide CRISPR-Cas9 screening method was recently used to discover a TCR that recognized the monomorphic MHC class I-related protein MR1 and T cells engineered to express this TCR killed several different types of human cancers without damaging healthy cells." (PMID 32903482, 2020).
bacterial infection (24 papers, 2010 to 2025). "MAIT cells were first characterized in MR1-dependent control of bacterial infections and more recently have been implicated in MR1-independent antiviral responses." (PMID 36845106, 2023). "Ablation of MR1 was found to result in increased susceptibility to a number of bacterial infections (14, 27, –, 29)." (PMID 35164552, 2022). "The MR1-restriction of MAIT cell activation was further confirmed by demonstrating a lower susceptibility of MR1-deficient mice to bacterial infections as well as the loss of MAIT cell-stimulating ability of bacteria lacking riboflavin biosynthesis enzymes." (PMID 33535703, 2021). "MR1-independent cytokine-driven responses to bacterial infection have been observed from circulating and liver-derived MAIT cells." (PMID 36085311, 2022). "Increased susceptibility to several bacterial infections, including M. bovis BCG and M. abscessus, in MR1 deletion mutant mice also highlights the important role of MAIT cells in antimicrobial immunity." (PMID 35164552, 2022). "This calls for more studies investigating the effect of SARS-CoV2 infection on MR1-dependent MAIT cell activation in response to secondary bacterial infections." (PMID 34238985, 2021). "The MAIT cell response is thus more likely to be IFN- and cytokine-activated, although involvement of MR1-restricted autoantigens or secondary bacterial infection or microbiota-derived antigens cannot be excluded at this time." (PMID 32989174, 2020). "A limitation of our approach is that we have been unable to anchor many of the molecular clusters so that many of the chemical structures of ions specific to MR1 loaded in the context of bacterial infection remain to be determined." (PMID 30006464, 2018). "MAIT cells can directly respond to bacterial infections by recognizing MR1-presented metabolites derived from the riboflavin synthesis pathway constituting a novel class of antigens." (PMID 30410474, 2018). "So, although there are two pathways of MAIT cell activation in response to bacterial infections, MR1-dependent and MR1-independent, the relative contribution of the two pathways is still unclear." (PMID 29176983, 2017). "In combination, these findings support the model that MR1 trafficking and ligand acquisition are likely altered by bacterial infection." (PMID 20613858, 2010). "MR1 presents metabolites in the context of host responses to bacterial infection." (PMID 39445059, 2024). "The main distinguishing feature of MAIT cells is their ability to recognize monomorphic MHC-1-related molecules (MR1), which present precursors from the riboflavin (RF) pathway present in many bacterial species, making them rapid responders to bacterial infection." (PMID 38003807, 2023). "Therefore, the combinatorial marker CD69+CD26++ is able to detect activated MAIT cells dependent on MR1-mediated antigen-presentation from Vα7.2+CD161+ population in bacterial infections." (PMID 32582206, 2020). "K562.hMR1 cells allow us to specifically detect bacterial-activated human MAIT cells and delineate MR1-dependent MAIT responses to bacterial infection, as different from bacterial-irrelevant cell activation by anti-CD3 antibody, cytokines, or autologous monocytes." (PMID 32582206, 2020). "MAIT cells respond to bacterial infection via the presentation of riboflavin metabolites by MR1." (PMID 30695101, 2019). "The key characteristic of MAIT cells is their ability to respond to bacterial infection via MR1." (PMID 24019201, 2014). "In summary, here we demonstrated that bacterial infection might provide a signal for endogenous MR1 proteins to be expressed on the cell surface." (PMID 24432025, 2014). "Taken together, these results demonstrated that bacterial infection might trigger MR1 to be expressed at the cell surface using mainly endocytic pathway." (PMID 24432025, 2014).
bacterial infection (continued). "Alternatively, it is possible that bacterial infection may alter the intracellular trafficking of MR1 and consequently determine which self or bacterial antigens are loaded and presented at the cell surface to MAIT cells." (PMID 20613858, 2010). "However, whether the MR1-5-A-RU tetramer also serves as a reliable tool to stain activated MAIT cells in bacterial infection is unknown." (PMID 32582206, 2020). "Similar to their response to bacterial infections, MAIT cells rely on the MR1‐dependent pathway to initiate responses in antifungal immunity as well." (PMID 41179703, 2025). "In relation to non-bacterial infections, MAIT cell response is mediated in an MR1-independent manner through the choreographed release of distinct cytokines." (PMID 38003807, 2023). "In a new bacterial infection, MAIT cells can be instantly activated by MR1-mediated antigen presentation bypassing a long priming stage for conventional T cells." (PMID 32582206, 2020). "To further understand the mechanism of MR1 up-regulation after bacterial infection, we examined the effect of LC and CCD on MR1 expression on E. coli-infected B-LCLs using flow cytometric assays." (PMID 24432025, 2014). "During bacterial infections, MAIT cell activation has been proposed to require T cell receptor (TCR)–mediated recognition of antigens derived from the riboflavin synthesis pathway presented by the antigen-presenting molecule MR1." (PMID 37516912, 2023). "Similarly, MR1 expression is almost undetectable in resting APC and it is upregulated following bacterial infection, likely due to stabilization of MR1 molecules by microbial antigens." (PMID 26284072, 2015). "In keeping with this, a recent case study reported an individual with a point mutation in MR1 and a lack of circulating MAIT cells who has a history of difficult to treat viral and bacterial infections, supporting an integral role for MAIT cell in host protection." (PMID 39128630, 2024). "Moreover, whether MR1-independent signals are sufficient to control MAIT cell functions in vivo during bacterial infections has not yet been addressed." (PMID 37516912, 2023).
infectious disease (6 papers, 2015 to 2026). A disorder directly resulting from the presence and activity of a microbial, viral, or parasitic agent in humans. "The importance of MR1 molecule and MR1-restricted cells has been described in a wide spectrum of infectious diseases caused by fungi, bacteria, and viruses." (PMID 39192975, 2024). "This has sparked interest in the potential to exploit the MR1-MAIT cell axis for the development of vaccines against infectious disease." (PMID 41746040, 2026). "In infectious diseases, APCs can present microbial-derived vitamin B metabolites via MR1 to TCR of MAIT cells." (PMID 30233587, 2018). "Finally, and perhaps of greatest importance, there is the question of whether MR1- or HLA-E-specific vaccination strategies can be developed for human infectious diseases." (PMID 36430890, 2022).
immune diseases (3 papers, 2018 to 2025). "The results showed that both groups had gender ratio, abnormal brain MR1 expression, serum AQP4-IgG-positive, and other immune diseases and symptoms." (PMID 35360267, 2022). "Studies using new tools such as MR1 tetramers and MR1 ligands may answer these questions and determine the potential of MAIT cells as a therapeutic target in immune diseases." (PMID 29942318, 2018).
neurodegenerative disease (2 papers, 2023 to 2024). A disorder of the central nervous system characterized by gradual and progressive loss of neural tissue and neurologic function. "Whereas roles for MR1 in infections and autoimmune responses have been established, considerably less information is available about MR1 in the context of neurodegenerative diseases in which neuroinflammation is often a characteristic." (PMID 39720231, 2024). "Like most of the neurodegenerative diseases discussed so far, there is a limited amount of data discussing any correlation between MR1 expression and the progression or overall pathology of MS." (PMID 39720231, 2024). "For example, chronic MR1-mediated MAIT cell activation and the subsequent secretion of proinflammatory cytokines have been shown to worsen the outcome of some neurodegenerative diseases." (PMID 39720231, 2024). "Although the evidence of the MR1/MAIT cell axis being involved in neurological diseases is compelling, to our knowledge, this is the first study that investigates this axis in a neurodegenerative disease." (PMID 36944969, 2023).
hematological disease (1 paper, 2022). "On the other hand, as an attractive target of MAIT cells, MR1 needs to be better explored for the mechanisms of hematological disease-associated antigens and antigen/MR1 complexes presented in MR1 to successfully target MAIT cells to tumors." (PMID 36052080, 2022).
MR1 also shares sentences with these, for which no sentence is quoted: Dystonia (2 papers); lymphoid cancer (2); Alzheimer disease (1); aplastic anemia (1); asthma (1); Ataxia (1); atherosclerosis (1); bladder cancer (1); cerebral palsy (1); clear cell renal cell carcinoma (1); clostridium difficile infection (1); co-infection (1); cognitive deficits (1); cutaneous melanoma (1); Dyskinesia (1); experimental autoimmune encephalomyelitis (1); fibrosis (1); gastric cancer (1); hemochromatosis (1); herpesvirus infection (1); Immunodeficiency (1); injury (1); Insulin resistance (1); Lewis lung carcinoma (1); liver cancer (1); lymphoblastic leukemia (1); meningitis (1); Merkel cell carcinoma (1); metabolic disease (1); monocytic leukemia (1).
A further 11 diseases each share a sentence with MR1 in 1 paper.